RORA (RAR related orphan receptor A)
Diseases named in the same sentence as RORA in open-access papers (continued):
Sharing a sentence is not in itself a finding about the gene and the disease.
autism (continued). "Male and female sex hormones differentially regulate the expression of a novel autism candidate gene, retinoic acid–related orphan receptor-alpha (RORA), which transcriptionally regulates aromatase." (PMID 32468248, 2020). "RORA is therefore an excellent candidate for future molecular studies of autism in Dup15q syndrome, a major portion of the phenotype." (PMID 29423132, 2018). "They observed decreased expression of RORα in the autistic brain and suggested RORA to be a novel candidate gene for autism pathogenesis." (PMID 28042538, 2017). "Given the role of RORA in the pathogenesis of nervous system disorders and its epigenetic impact on the incidence of autism, we aimed to investigate the methylation of the RORA promoter region in autistic cases." (PMID 28042538, 2017). "CD38 and acid-related orphan receptor alpha (RORA) mRNA levels were used to assess autism-related biochemical indicators’ changes." (PMID 28938872, 2017). "This study applied the MCA-Meth assay on the lymphocyte cells of 30 autistic children in order to confirm the increased methylation of the promoter region of RORA gene and the consequent mRNA expression in autism pathogenesis in the Isfahan population." (PMID 28042538, 2017). "In a neuronal cell model, we have demonstrated that RORA can bind to the promoter regions of over 2,500 genes, 438 of which are included in autism gene databases." (PMID 26056561, 2015). "This exploratory study on sex differences in the ASD brain examines the sexually dimorphic expression of RORA, a functionally relevant candidate gene for autism, in the postmortem brain tissues of humans and mice, focusing on the frontal cortex and cerebellum." (PMID 26056561, 2015). "In subjects with autism, gene expression of RORA was reduced as was expression of RORA protein in post-mortem samples of the cerebellum and frontal cortex." (PMID 26066795, 2015). "This is particularly relevant since over 400 of the identified transcriptional targets of RORA are listed in SFARI Gene and AutismKB databases as autism candidate/susceptibility genes." (PMID 26056561, 2015). "Together, these results link these molecular changes in RORA in blood-derived peripheral cells to molecular pathology in the brain tissues of individuals with autism." (PMID 23697635, 2013). "Nevertheless, the data from this limited sampling of cases and controls suggest a trend towards reduced expression of transcriptional targets in autism brain tissues exhibiting reduced RORA." (PMID 23697635, 2013). "Using this method we identified associations with SNPs at the P<10−4 level in or near several genes previously implicated in autism: NLGN4X, RAPGEF4, RORA, FAM135B and CNTNAP2." (PMID 24204716, 2013). "The notion that RORA methylation might be largely responsible for the language deficits sometimes associated with ASD is a useful finding that helps clarify the etiology of autism and an important first step in determining the particular mechanism responsible for these symphtoms." (PMID 24151554, 2013). "Because RORA is a hormone-dependent transcription factor that is involved in a variety of functions impacted in autism, we sought to investigate the effects of both male and female hormones on RORA expression." (PMID 21359227, 2011). "Here, we show that male and female hormones differentially regulate the expression of a novel autism candidate gene, retinoic acid-related orphan receptor-alpha (RORA) in a neuronal cell line, SH-SY5Y." (PMID 21359227, 2011). "In our snRNA-seq dataset, of all tested diseases, genes associated with autism (DOID:12849) were overrepresented (Fisher’s exact test, OR = 10.2, Padj = 8.52 × 10−16) among the top 100 Purkinje cell marker genes, including RORA [fold change (FC) = 331.9], AUTS2 (FC = 43.1), and SHANK2 (FC = 13.8)." (PMID 37824616, 2023).
autism (continued). "IEC-specific RORA deficiency either mimicked or worsened maternal diabetes-mediated GI symptoms as well as oxidative stress and inflammation in IEC, while there was little effect on maternal diabetes-mediated autism-like behaviors." (PMID 35164690, 2022). "We then hypothesize that RORA may play a role in GI symptoms in maternal diabetes-mediated autism-like mouse offspring through pathways involving the suppression of RORA and its target genes CYP19A1 and SOD2 in the gut system." (PMID 35164690, 2022). "We conclude that intestine-specific RORA deficiency does not affect maternal diabetes-mediated autism-like behaviors." (PMID 35164690, 2022). "This was further supported by in vivo mouse study through maternal diabetes-mediated RORA suppression in brain tissues from autism-like offspring, indicating that hyperglycemia memory may play an important role in maternal diabetes-mediated ASD development." (PMID 35027651, 2022). "Furthermore, we have early found that maternal diabetes-mediated autism-like mouse offspring has reduced RORA expression in some brain regions as well as in intestinal epithelial cells (IEC)." (PMID 35164690, 2022). "We suppose that maternal diabetes-mediated RORA suppression in PBMC may contribute to GI symptoms in autism-like offspring by modulation of systemic inflammation in PBMC cells." (PMID 35164690, 2022). "The aim of this study is to assess the hypothesis suggesting RORA silencing in autistic children by conducting a study on three pairs of discordant MZ twins for autism using microarray screening method and MSP confirmation." (PMID 28042538, 2017). "Recently, Hu and colleagues have proposed a new candidate gene for autism: the retinoic acid-related orphan receptor α (RORA), a ligand-dependent orphan nuclear hormone receptor which binds DNA of target genes and regulates expression of these genes in cooperation with co-regulator proteins." (PMID 26066795, 2015). "Methylation profiling of lymphoblastoid cell lines from three sets of identical twins discordant for autism revealed epigenetic differences and led to the identification of a novel autism candidate gene, RORA, whose protein product was reduced in autistic brain samples." (PMID 24737292, 2014). "Nevertheless the methylation of RORα promoter region may not be considered as a common epigenetic risk factor for autism in all populations." (PMID 28042538, 2017). "Collectively, RORA may be seen as a candidate gene for autism sensitivity." (PMID 28042538, 2017). "We evaluated the effects of RORA agonist and SOD mimetic MnTBAP on maternal diabetes-mediated autism-like behaviors." (PMID 35164690, 2022). "We conclude that RORA agonist and SOD mimetic ameliorate maternal diabetes-mediated autism-like behaviors in male offspring." (PMID 35164690, 2022). "SOD mimetic MnTBAP completely, while RORA agonist SR1078 partly, reversed maternal diabetes-mediated autism-like behaviors, indicating that maternal diabetes-mediated oxidative stress plays a major role." (PMID 35164690, 2022). "The RORα agonist SR1078 recently was shown to be well tolerated and efficacious in an animal model of autism and our present study indicates that this agonist is active in normoxic and hypoxic cardiomyocytes." (PMID 34756888, 2021). "We have recently identified a novel autism candidate gene, retinoic acid-related (RAR) orphan receptor-alpha (RORA), which is a hormone-dependent transcription factor." (PMID 21359227, 2011). "Studying twins where one sibling has autism and the other does not, revealed increased CpG island methylation at the upstream RORα promoter sites of the twin with ASD." (PMID 41245836, 2025). "An in vitro study also demonstrated that RA can upregulate CD38 transcription levels; RA may regulate RORs (including RORA, RORB, RORR) through its retinoic acid receptors, which demonstrated the potential role of VA in autism biomarker." (PMID 28938872, 2017).
autism (continued). "Treatment with decitabine was shown to demethylate promoters and restore/induce the expression of the silenced RORA and BCL2 in autistic and patients with fragile X syndrome and hence, the use of DNA demethylating agents in drug therapy for autism and fragile X syndrome has been suggested." (PMID 24238559, 2013). "RORA has the potential to be under both negative and positive feedback regulation by male and female hormones, respectively, through one of its transcriptional targets, aromatase, suggesting a mechanism for introducing sex bias in autism." (PMID 41245836, 2025). "RORα and its inverse processes, including REV-ERB (reverse orientation the c-erbA-1 gene) nuclear receptors, may be targeted using synthetic ligands for treating several diseases, including atherosclerosis, nonalcoholic steatohepatitis (NASH), and autism." (PMID 32392803, 2020). "We have recently identified a novel autism candidate gene, retinoic acid-related (RAR) orphan receptor-alpha (RORA) which is regulated by male and female hormones in a manner that may provide an explanation for the higher testosterone levels and, possibly, sex bias in ASD." (PMID 23697635, 2013). "Interestingly, other autism candidate genes, including NLGN3, NRXN1, RELN, and GABAA, were also included in the predicted gene network, thus supporting the investigation of our selected genes as ASD-relevant transcriptional targets of RORA." (PMID 23697635, 2013). "The regulation of RORA and its transcriptional targets, including CYP19A1, is tightly regulated in the male cortex but less so in females, suggesting that RORA dysregulation could have greater impact on E2 and testosterone regulation and aromatase activity in cortex of male autism patients." (PMID 27870449, 2017).
asthma (31 papers, 2011 to 2025). "In human studies, there is an association of RORα with asthma, with RORA expressed in T cells of the airways of healthy and asthma patients." (PMID 37387671, 2023). "Recently, RORα has been associated with allergic diseases as its expression level was found to be on the higher side in patients with therapy-refractory asthma along with RORα rs11071559C>T gene polymorphism accounting for elevated susceptibility to asthma." (PMID 33574813, 2020). "We replicated previous GWAS results, reporting a significant association of TSLP and RORA gene variants with asthma and GCKR, PNPLA3, TRIB1 and TM6SF2 gene variants with the risk of developing liver diseases, notably NAFLD/NASH." (PMID 30978214, 2019). "The 15q21 has already been described in GWA of asthma, with the most associated genes being RORA, SMAD3 and SCG3." (PMID 26635092, 2015). "In humans, RORA encodes four isoforms (RORA-1, RORA-2, RORA-3, and RORA-4), and the asthma-associated single nucleotide polymorphism (SNP) rs11071559 is located in the first intron of the transcript variant encoding RORA-1." (PMID 23565190, 2013). "The fact that the association signals were found in two separate datasets of European children and were further observed in the combined dataset support RORA as a susceptibility gene for asthma." (PMID 23565190, 2013). "The genetic association between RORA rs11071559 and asthma susceptibility was identified in a GWAS of individuals with European descent, and further confirmed in other populations." (PMID 23565190, 2013). "Similar results were observed for RORA SNP rs8024629 and RORA SNP rs9302215 which only increase the risk of asthma in individuals carrying the functional haplotype CAC in NPSR1 (rs2530547C/rs324981A/rs727162C)." (PMID 23565190, 2013). "Here, we replicate the effects of RORA rs11071559 on asthma-susceptibility and discover additional asthma-susceptibility alleles in the surroundings of this SNP." (PMID 23565190, 2013). "Retinoid acid receptor-related Orphan Receptor Alpha (RORA) was recently identified as a susceptibility gene for asthma in a genome-wide association study." (PMID 23565190, 2013). "The association between the lead SNP rs7164773 and asthma was significant after adjustment for the other asthma-associated SNPs RORA rs11071559 and RORA rs341392." (PMID 23565190, 2013). "Genetic variants in RORA have also been associated with risk of allergic rhinitis and multi‐trigger wheeze, with asthma and allergy markers in an admixed population, and with the regulation of T helper‐2 (Th2) cells that are closely involved in the pathogenesis of allergic asthma." (PMID 40133993, 2025). "Notably, among the predicted upstream regulators were IL-33 and the transcription factor retinoic acid-related orphan receptor α (RORA), both shown to significantly contribute to the pathogenesis of asthma in a recent genome-wide association study." (PMID 26740570, 2016). "In addition, genes discovered in genome-wide association studies of asthma (RORα, IL-13, IL-33, IL-1RL1; which are all related to ILC2) suggest a key role for ILC2 in asthma." (PMID 26727464, 2016). "Although the underlying mechanisms are unknown, the functional link of RORA with the pathogenesis of early-onset asthma might involve alterations in lung development." (PMID 23565190, 2013). "Even though RORA was recently identified as an asthma susceptibility gene in a GWAS study, its role in asthma pathogenesis is unknown." (PMID 23565190, 2013). "In addition, mice deficient in RORα or RORγ displayed a diminished susceptibility to allergen-induced lung inflammation and collagen-induced arthritis and polymorphisms in RORα have been associated with increased susceptibility to asthma." (PMID 23355833, 2013). "Similarly, RORA has an established role as a risk gene for asthma." (PMID 40133993, 2025).
asthma (continued). "Notably, the association of RORA rs7164773 with asthma might depend on the convergence with rare alleles of the NPSR1 SNPs rs6972158 on chromosome 7." (PMID 23565190, 2013). "Expression levels of HLA-DQA1/A2 (P = 0.0077), ORMDL3 (P = 0.0021), and RORA (P = 0.0005) were significantly lower in severe asthma subjects only compared to controls." (PMID 35386986, 2021). "RORα has also been linked with allergic and autoimmune diseases, with RORA implicated in the development of asthma and also increased susceptibility to multiple sclerosis." (PMID 32973801, 2020). "Three known asthma loci replicated in CAAPA, after a Bonferroni correction for 810 association tests: chromosomes 9p24 (RANBP6, IL33), 15q22 (RORA,NARG2,VPS13C), and 17q12–q21." (PMID 30787307, 2019). "Since both RORA and NPSR1 are independently associated with asthma, we evaluated the potential epistasis between polymorphisms in these genes (‘gene-gene interactions’)." (PMID 23565190, 2013). "The asthma-associated SNPs, albeit different between BAMSE and PARSIFAL, were confined into a region of 49 kb in the intron 1 of RORA (chr15∶61020254–61069988) and their effects were mainly detected under dominant and additive models." (PMID 23565190, 2013). "The Retinoic acid receptor-related Orphan Receptor Alpha (RORA; MIM 600825, chromosome 15q22.2) was recently implicated in asthma susceptibility by a genome-wide association study (GWAS)." (PMID 23565190, 2013). "RORA is mostly known for its functions as a regulator of circadian rhythms, metabolism, as well as mood disorders, and its role in the immune system and asthma has gained attention only recently." (PMID 23565190, 2013). "Among the asthma genes identified in genome wide association studies, ROBO1, RORA, HLA-DQB1, IL2RB and PDE10A were differentially expressed during human lung development." (PMID 21699702, 2011). "Genetic association studies have uncovered those variations within the IL33 gene, the ST2 (IL1RL1) receptor, the ROR-α (RORA) transcription factor, and IL13—all pivotal in the development and activation of ILC2s—are linked to asthma with a high presence of type 2 helper T cells." (PMID 38680486, 2024). "In particular, we identified strong environmental interactions with asthma risk SNPs near the DENND1B and RORA genes and strong environmental interactions with alopecia areata, Crohn’s disease, membranous neuropathy, neuroblastoma, and systemic lupus erythematosus in several immune system genes." (PMID 26170196, 2015). "RORα expression was significantly upregulated in patients with therapy-resistant asthma." (PMID 26878025, 2015). "Based on the results indicating up-regulation of RORA mRNA expression after NPS stimulation of NPSR1 over-expressing cells, and the observation that NPSR1 is down-regulated by RORA, we studied the effects of gene-gene interaction between RORA and NPSR1 SNPs on the risk of asthma." (PMID 23565190, 2013). "Novel interactions between genes were suggested and replicated, such as between ORMDL3 and RORA, where certain genotype combinations gave odds ratios for current asthma of 2.1 (95% CI 1.2-3.6) and 3.2 (95% CI 2.0-5.0) in the BAMSE and PARSIFAL children, respectively." (PMID 24260339, 2013). "Asthma GWAS have identified a robust set of genes that are consistently associated with the disease in diverse populations (e.g. the IKZF3-ZPBP2-GSDMB-ORMDL3 locus, TSLP, and RORA), as well as genes that seem to be race/ethnicity specific (e.g. PYHIN1)." (PMID 23984888, 2013). "We also examined three SNPs where previous evidence was strongly suggestive (P<5×10−7 for association with asthma) but not genome-wide significant, and one of them, rs11071559 in RORA, is strongly supported in our data (Reported P = 1.1x10−7; PAPCAT = 0.0031)." (PMID 23028483, 2012). "Furthermore, RORA expression was upregulated in patients with therapy-resistant asthma." (PMID 37387671, 2023).